CDKN2A (cyclin dependent kinase inhibitor 2A)
Diseases named in the same sentence as CDKN2A in open-access papers (continued):
Sharing a sentence is not in itself a finding about the gene and the disease.
melanoma (continued). "P16 may be inactivated by homozygous deletions or methylation of the promoter region, and this phenomenon commonly occurs in families with melanoma aggregation, while CDKN2A mutations are registered less frequently in primary tumors associated with sporadic cases." (PMID 38667459, 2024). "In addition to their risks for melanoma and pancreatic cancer, carriers of CDKN2A variants may face moderate risks for breast, lung, and esophageal cancer." (PMID 38961426, 2024). "Additionally, it has been shown that CDKN2A mutations that cause loss of function in somatic cells are linked to lung, head and neck, gastroesophageal, melanoma, stomach, colon, and non-small cell lung cancers, indicating that CDKN2A is involved in a number of tumor types." (PMID 38206516, 2024). "Rare mutations in high penetrance genes are responsible for melanoma symptoms in about 22% of melanoma families (19% for CDKN2A and 3% for other genes), while the significant melanoma genetic factors underlying melanoma in melanoma-prone families are still unknown." (PMID 39335684, 2024). "Therefore, the broad spectrum of cancer phenotypes potentially accompanying the germline alterations in CDKN2A suggests that it could be regarded as a candidate for tumor predisposition beyond melanoma and pancreatic cancer in clinical practice." (PMID 36805510, 2023). "Patients with FAMMM (mainly associated with alteration of the CDKN2A gene, involved in cell cycle regulation), clinically characterized by the presence of atypical nevi and a total body nevi count > 50, have a very high risk of melanoma, ranging from 28% to 67%." (PMID 37239385, 2023). "As estimates have suggested that POT1 may be the second major high-penetrance melanoma susceptibility gene after CDKN2A, being causal of disease predisposition in 2%–4% of CDKN2A/CDK4-negative families, 14 it has been included in multiple panels for genetic testing of melanoma families." (PMID 36539277, 2023). "In addition, in vitro studies have shown that CDKN2A mutated melanomas may benefit from CDK4/6 inhibitors, and this therapy may be beneficial for patients with acquired resistance to BRAF/MEK inhibitors." (PMID 37373134, 2023). "Interestingly, MC1R variants may substantially increase the penetrance of CDKN2A mutations and the risk of melanoma in affected families, particularly multiple MC1R variants and red hair color variants." (PMID 35465855, 2022). "In addition, a splicing variant in CDKN2A (NM_000077.4:c.151–1G>C), responsible for loss of p16INK4a and p14ARF has been reported in a number of families affected by multiple neoplasms, including nerve sheath tumors and melanomas." (PMID 35723634, 2022). "However, in the case of hereditary melanoma, there are indications that genetic testing in children could be justified in the case of CDKN2A gene mutations." (PMID 35465855, 2022). "Furthermore, these two mouse tumors and the cell lines had either a deletion in exon 2 of the Ink4a/Arf gene or an interstitial deletion of the long arm of chromosome 4 (where the Ink4a/Arf gene resides), similar to genetic changes of human melanoma for CDKN2A, encoding p16INK4a and p19ARF." (PMID 36291794, 2022). "Studies have also demonstrated a potential role of cell cycle regulation in both endometriosis and melanoma including the role of increased proliferation and decreased apoptosis in endometriosis progression, and risk loci located near known cell regulators, like CDKN2A, in both diseases." (PMID 36304021, 2021). "Finally, cladribine, an FDA-approved multiple sclerosis treatment drug, is selected and identified as a repurposable drug for treating melanoma with CDKN2A mutation by in vitro validation, serving as a demonstrating SLKG utility example for novel tumor therapy discovery." (PMID 33627666, 2021). "In addition, variants of the MC1R gene increase the melanoma risk in CDKN2A mutation carriers." (PMID 34571969, 2021).
melanoma (continued). "In addition, CDKN2A loss in 50–60% metastatic tumors increases the risk of melanoma development." (PMID 34361615, 2021). "Together, our data suggest that the reduced expression of SALL4 induces human melanoma cell invasion via upregulation of known melanoma invasiveness genes, which could explain the increased metastasis burden seen upon Sall4 loss in the Tyr::NrasQ61K; Cdkn2a−/− melanoma mouse model." (PMID 34417458, 2021). "However, the expanded spectrum of phenotype accompanying germline alterations in CDKN2A suggests that it may be relevant to consider CDKN2A as a candidate for tumor predisposition beyond melanoma and pancreatic cancer in clinical practice." (PMID 33766116, 2021). "In summary, rare mutations in high-penetrance genes account for melanoma manifestation in approximately 22% of melanoma families (19% for CDKN2A, and 3% for the other genes), while the major melanoma genetic factors underlying melanoma in prone families are still unknown." (PMID 34356093, 2021). "Promoter hypermethylation of CDKN2A leading to transcription silencing and loss of protein expression increases during melanoma progression and has been identified in approximately 19–60% of vertical-growth-phase melanomas, 40% of radial-growth-phase melanomas, and 25–33% of melanoma metastases." (PMID 33076392, 2020). "Factors other than CDKN2A mutations may have contributed to melanoma risk." (PMID 32760473, 2020). "Conversely, the prevalence of CDKN2A alterations (19/32; 59.4%)—which include inactivating gene mutations, exon deletions, and amino acid substitutions—was much higher in cell lines derived from melanoma metastases (16/24; 66.7%) than in those derived from primary melanomas (3/8; 37.5%)." (PMID 29492214, 2018). "HGF/SF melanomas also exhibit a number of other characteristics that resemble the human form of the disease, such as the junctional activity observed between melanoma and epithelial cells in skin, and loss of the tumor suppressor CDKN2A during malignant progression." (PMID 28788083, 2017). "Interestingly, several studies have reported associations between melanoma and breast cancer, finding either a higher risk of breast cancer following melanoma diagnosis or the opposite, and a higher breast cancer risk was reported in melanoma-prone families carrying CDKN2A mutations." (PMID 24915306, 2014). "Furthermore, MC1R variants are a modifying factor for melanoma risk in CDKN2A mutation carriers, suggesting that multiple medium- and low-penetrance genes may influence the risk conferred by high penetrance melanoma genes." (PMID 24742402, 2014). "Patient B is a boy of 7 years when treated for astrocytoma then developing melanoma associated to congenital nevi on the head 10 years later: sequencing and multiplex ligation-dependent probe amplification revealed a normal profile of the CDKN2A/CDKN2B/CDKN2BAS region." (PMID 24884915, 2014). "Familial melanoma was significantly associated with the earlier age of onset, lower Breslow thickness and with a higher number of in situ melanomas; and also carriers of CDKN2A mutations were associated with a higher risk of multiple melanomas and cytoplasmic survivin immunostaining." (PMID 25893138, 2014). "A study based on 80 melanoma-prone families consisting of 402 melanoma patients and 713 non-affected family members from North America, Europe, and Australia was used by the Melanoma Genetics Consortium to calculate the lifetime projected risk of developing the disease in CDKN2A carriers." (PMID 23372575, 2012).
melanoma (continued). "The first clues about the molecular basis of melanoma came from studies of families prone to the disease and the identification of two autosomal-dominant high-susceptibility loci: cyclin-dependent kinase inhibitor 2A (CDKN2A) and cyclin-dependent kinase 4 (CDK4)." (PMID 22339359, 2012). "The melanoma genetics consortium (Genome) studied the relationship between pancreatic cancer and familial melanoma and found that the occurrence of pancreatic carcinoma significantly predicted the likelihood of finding CDKN2A mutations, with the exception of Australia." (PMID 24281082, 2010). "In addition, loss of PTEN protein and oncogenic activation of NRAS seem to be mutually exclusive and both alterations may cooperate with the loss of CDKN2A expression in contributing to melanoma tumorigenesis." (PMID 19828018, 2009). "Melanoma-private mutations in genes such as ARID1A, ARID2, PIK3CA, and CDKN2A indicated additional late events contributing to malignant progression." (PMID 41516405, 2026). "The CDKN2A is a frequently inactivated tumor suppressor gene, e.g. it is the most commonly inactivated tumor suppressor gene in melanoma." (PMID 41438586, 2026). "Nevi most often harbored canonical MAPK-pathway mutations in BRAF and NRAS, as well as in GRIN2A, while melanomas, along with BRAF and NRAS, frequently carried additional driver alterations in ARID1A, ARID2, CDKN2A, and PTEN." (PMID 41516405, 2026). "The combined loss of CDKN2A and MTAP is a recurrent event in several malignancies, including mesothelioma, glioma, and melanoma, suggesting a broader biological linkage within the 9p21 locus." (PMID 41596618, 2026). "Inactivation of the gene group CDKN2A/B is a common phenomenon in cancer such as in melanoma, and gene inactivation has been reported to occur in the range of 40% to 70%." (PMID 41438586, 2026). "The authors, therefore, concluded that CDKN2A suppresses melanoma invasion by preventing the E2F1-mediated upregulation of BRN2, thereby identifying a key axis in melanoma progression." (PMID 41596618, 2026). "Using DNA isolated by laser-captured microdissection from the atypical nevi of 10 melanoma patients and their spouses as matched controls, researchers sequenced exons 1 and 2 of the CDKN2A gene." (PMID 41596618, 2026). "Skin melanomas showed a higher frequency of specific gene alterations such as CDKN2A deletion (P < .05), BRAF single-nucleotide variants (SNVs; P < .01), and TERT promoter variants (P < .01) than mucosal melanomas." (PMID 39823560, 2025). "In melanoma prone families, pancreatic cancer was observed in 28% of CDKN2A‐mutant kindreds compared to only 6% of CDKN2A‐wild‐type kindreds." (PMID 39609109, 2025). "Variants in CDKN2A, CDK4, and MC1R—such as G101W, A148T, and R24C—have been associated with melanoma in populations from Poland, Spain, and the United Kingdom (UK) as well as in Brazilian and Austrian populations." (PMID 40429816, 2025). "This is clearly inaccurate: CDKN2A and CDK4 (MIM: 123829) PTVs are associated with malignant melanoma, and VHL (MIM: 608537) is associated with kidney cancer." (PMID 40073867, 2025).
melanoma (continued). "Of note were the complete tumor regressions observed in the YUMM1.7 model, a more clinically relevant murine model that harbors important molecular aberrations observed in human melanoma (including in Braf V600E, and inactivated Cdkn2a and Pten)." (PMID 40638246, 2025). "To induce melanoma, we combined Cdh1 loss with the NRAS(Q61K) mutation using the Tyr::NRASQ61K/°; Cdkn2a+/− model." (PMID 40500450, 2025). "The CDKN2A acts as a tumour suppressor that regulate the cell cycle and its inactivation, commonly observed in melanomas, results in unchecked cell cycle progression." (PMID 40867317, 2025). "Germline variants in CDKN2A, CDK4, BAP1, POT1, ACD, TERF2IP, and TERT have been identified as high-penetrance variants associated with melanoma development." (PMID 40429816, 2025). "It was recently reported that several DNPS genes are essential for the survival of melanoma cells which lost p16/CDKN2A." (PMID 40097378, 2025). "CDKN2A is a tumor suppressor gene, and the CDKN2A locus is commonly lost in the development of invasive melanoma and melanoma metastases." (PMID 40457397, 2025). "Genetic mutations in KRAS, NRAS, and BRAF were commonly implicated in the development of both melanoma and CRC, while mutations in CDKN2A and BRCA2 were specifically significant in melanoma." (PMID 40447784, 2025). "Variants in TYR, TYRP1, CDKN2A, and HERC2 significantly contributed to risk, and light brown eye and hair colors were strongly associated with increased melanoma risk." (PMID 40429816, 2025). "In fact, a germline mutation in CDKN2A gene can be responsible for the development of the familial atypical multiple mole and melanoma syndrome (FAMMM), which is characterized by melanomas and pancreatic cancer development." (PMID 39609109, 2025). "The gene encoding the cyclin-dependent kinase inhibitor 2A (CDKN2A) is frequently lost or mutated in 40-70% of sporadic melanoma tumors, and 20-40% of familial melanomas." (PMID 40904502, 2025). "The 2023 Italian guidelines recommend testing for the CDKN2A gene in individuals with multiple melanoma diagnoses or a significant family history of the condition." (PMID 40558591, 2025). "In familial melanomas, up to 40% harbor CDKN2A mutations, leading to deficiencies in the p14ARF and p16INK4A proteins." (PMID 40331942, 2025). "MPMs are more common in individuals with CDKN2A or CDK4 variants and typically present at a younger age compared to sporadic melanomas." (PMID 39941357, 2025). "Multigene panel testing, including genes like CDKN2A, CDK4, BAP1, POT1, ACD, and TERF2IP, enhances the detection of hereditary melanoma risk." (PMID 39941357, 2025). "While known high-penetrance genes, such as CDKN2A, explain some cases, a substantial proportion of hereditary melanoma remains genetically undefined." (PMID 40851494, 2025). "In our previous study, haplotype analyses of CDKN2A and SLC45A2 were significantly associated with melanoma risk in Colombian patients." (PMID 40429816, 2025).
melanoma (continued). "Loss of the tumor suppressor gene, cyclin-dependent kinase inhibitor 2A (CDKN2A), is a frequent driver of melanoma progression." (PMID 40981345, 2025). "Genetic mutations in KRAS, NRAS, and BRAF were frequently observed in both melanoma and CRC, whereas BRCA2 and CDKN2A mutations were specific to melanoma." (PMID 40447784, 2025). "Melanoma development can be influenced by mutations in several genes, such as CDKN2A (p16), CDK4 (found on chromosome 12q15), RB1, CDKN2A (p19), and PTEN/MMAC1 that can be targeted for systemic therapy." (PMID 40344340, 2025). "Among the 161 CDKN2A/CDK4/BAP1-negative melanoma families included in this cohort, only one likely PV in POT1 (c.676C > A, p.His226Asn) was identified (0.6%)." (PMID 40851494, 2025). "CDKN2A is an unstable gene, whose alterations are frequently observed in cancers, such as head and neck cancer, melanoma, and lung cancers." (PMID 39914044, 2025). "In a previous analysis of a Norwegian melanoma‐prone family, we identified a large 10 kb deletion removing CDKN2A exon 1α and half of exon 2 (breakpoint inside exon 2)." (PMID 40072281, 2025). "Moreover, it was also shown that adipocyte EVs carrying β-catenin could block the transcription of CDKN2A factor (responsible for cell growth regulation) and decrease p16INK4A levels (associated with cell cycle regulation) in melanoma cells, which resulted in tumor progression." (PMID 39697630, 2024). "We next performed a secondary dropout screen in the Yumm5.2 mouse melanoma isogenic pair with Cdkn2a knockdown, using a cell metabolism-focused library." (PMID 38626341, 2024). "Only EMSY was recurrently affected by BA-SVs in both cutaneous and mucosal melanomas, and only CDKN2A and CDKN2B were recurrently affected by BA-SVs in both acral and cutaneous melanomas." (PMID 38758740, 2024). "Clinical study also shows that CDKN2A methylation, mutation, or loss of p16 (INK) protein are associated with increased melanoma susceptibility to CDK4/6 inhibitor Palbociclib." (PMID 38822443, 2024). "All eight cases of multiple/familial primary mucocutaneous melanomas with CDKN2A homozygous deletion corresponded to a total score ≥9." (PMID 38667459, 2024). "In melanoma, BRAF and NRAS mutations promote cell proliferation by activating the MAPK/ERK pathway, while CDKN2A mutations further enhance tumor cell proliferation by removing inhibition of the cell cycle." (PMID 39581873, 2024). "The most mutated genes, which are associated with the development of resistance to targeted therapy in melanoma include CDKN2A, RB1, PIK3CA, AKT3, HOXD8, PAX5, MAP3K8, and MITF." (PMID 38275910, 2024). "A correlation has been shown between NRAS mutation and loss of CDKN2A expression through promoter hypermethylation, potentially explaining the loss of p16INK4A in BRAF/MEK inhibitor-resistant melanoma with NRAS mutations." (PMID 39501277, 2024). "Germline mutations in CDKN2A and CDK4 can significantly elevate an individual’s lifetime risk of developing melanoma." (PMID 39200315, 2024). "While melanomas commonly harbor losses of 9p21, on which CDKN2A resides, the presence of additional tumor suppressor elements at this locus is incompletely characterized." (PMID 39138582, 2024). "A total score of at least 9 out of 10 points per tumor defined melanomas with homozygous CDKN2A deletions, exhibiting a sensitivity of 100% and specificity of 94.11%." (PMID 38667459, 2024).